CCL2 (C-C motif chemokine ligand 2)
Diseases named in the same sentence as CCL2 in open-access papers (continued):
Sharing a sentence is not in itself a finding about the gene and the disease.
tumor (continued). "The use of a CCL2 inhibitor, pirfenidone, can enhance the anti-tumor effect of palbociclib." (PMID 41463246, 2025). "Inhibiting glycolysis reduces the tumor cell–secreted CCL2 levels." (PMID 39883522, 2025). "The balance of pro-tumor and anti-tumor TAMs is altered by mIL12 mRNA treatment and appears to be associated with baseline TAM infiltration and levels of the macrophage inducing cytokine CCL2." (PMID 40560386, 2025). "In addition, tumor-derived signals such as TNF-α induce TAMs to secrete chemokines (CCL2, CCL8) that recruit CCR2+ monocytes, amplifying the pro-tumoral milieu and enhancing immune evasion in NSCLC." (PMID 41584608, 2025). "However, with a deeper understanding of the complexity of TME, studies have found that the pro-tumor properties of CCL2 far outweigh the anti-tumor effects." (PMID 41341593, 2025). "Furthermore, tumor cells actively shape the immune microenvironment by secreting immunomodulatory cytokines such as CCL2, M-CSF, TNF, IL-10, and TGF-β, thereby amplifying the recruitment and M2 polarization of TAMs." (PMID 41459539, 2025). "In mice, inducible non-classical monocytes can migrate into both vascular and extravascular tumor microenvironments via the CCR2/CCL2 axis, where they release CCL6 to recruit NK cells that promote tumor lysis independent of T and B lymphocytes, attenuating metastasis." (PMID 40427136, 2025). "CCL2 is well-known for its ability to attract macrophages into the tumor microenvironment." (PMID 40083697, 2025). "During initial tumor development, malignant cells recruit macrophages through paracrine secretion of cytokines and chemokines, including granulocyte–macrophage colony‐stimulating factor (GM‐CSF), CCL2, and CXCL4." (PMID 41427020, 2025). "Some studies have revealed the regulation of CCL2 production by the interaction between tumor cells and stromal cells, but the mechanisms are mostly unknown and deserve further investigation." (PMID 41341593, 2025). "Here, we showed that lung fibroblast activated by DKK1 actively produced IL-6 and CCL2, which are representative cytokines identified as the iCAF markers, which raise a notion that iCAFs are activated and promote tumor progression in high DKK1-expressing tumors." (PMID 40025612, 2025). "CCL2 further recruits monocytes/macrophages, promoting tumor survival." (PMID 40430894, 2025). "Additionally, studies have shown that a tumor adaptation mechanism exists whereby the Ccl2/Ccr2/Cxcl2 axis promotes the recruitment of monocytes which in turn can acquire pro-tumorigenic phenotypes and contribute to immunosuppression." (PMID 40568084, 2025). "Since the levels of sCD163 act as surrogates of the TAMs’ tumor burden, and CCL2 along with CCL4 are well-studied chemoattractant cytokines for TAMs’ infiltration, we hypothesize that TAMs play an important role in WM pathogenesis." (PMID 39996747, 2025). "Additionally, CCL2 also facilitates tumor immune escape by recruiting regulatory T cells (Tregs) and myeloid-derived suppressor cells (MDSCs) to inhibit anti-tumor immune." (PMID 40918470, 2025). "In order to reduce the immunosuppressive effects in the TME and enhance the anti-tumor immune response, future studies may focus on fine-tuning the CCL2/CCR2 pathway." (PMID 41376630, 2025). "Additionally, the elevated TIDE score in the high-risk group suggests T cell exhaustion, potentially associated with high PD-L1 expression in suppressive cells or tumor cell-secreted chemokines (e.g., CCL2) recruiting suppressive cells." (PMID 40697378, 2025). "Previous research has revealed that OSMR’s participation in cancer is strongly tied to the JAK/STAT3 signaling pathway, and that inhibiting the STAT3/CCL2 signaling pathway may inhibit tumor malignancy." (PMID 40161370, 2025). "Therefore, targeting CCL2 signaling represents a promising strategy for the development of tumor immunotherapies." (PMID 40806751, 2025).
tumor (continued). "Similarly, CXCL1 and CCL2 enhance the infiltration of monocytes and dendritic cells, reinforcing the tumor-suppressive effects of senescence." (PMID 41463272, 2025). "The provided important evidence that at least the efficacy of CD8 + TCA may require the CCL2-CCR2 and/or CCL22-CCR4 axes, is in accordance with earlier observations on CCL2-dependent tumor tropism of adoptively transferred T cells." (PMID 40595293, 2025). "In the current approach, CCL2 is intended to attract M2-like macrophages located in the tumor periphery toward the cryogel, where they will come into contact with interleukin-12 (IL-12) and interferon gamma (IFN-γ) and be polarized toward M1-like characteristics." (PMID 40883548, 2025). "It is widely acknowledged that chemokines secreted by tumor cells such as CCL2, CCL5, CCL7, CCL20, CXCL2, CXCL8 and CXCL12 significantly contribute to the recruitment of monocytes and macrophages during neoplastic transformation, among which CCL2 plays a key role in TAM recruitment." (PMID 40380196, 2025). "Together, these results showed that adipocyte-secreted CCL2 contributed to cisplatin resistance through both paracrine signaling to tumor cells and autocrine stimulation of lipolysis in adipocytes, with both pathways being effectively targeted by CCR2 blockade." (PMID 41276817, 2025). "Ccl2 is known to promote M2-polarization of macrophages, which in turn promotes tumor angiogenesis." (PMID 39566333, 2025). "Furthermore, recent research investigating MC-tumor cell interaction-related genes and microRNA expression profiles underscores the clinical relevance of CCL2 signaling and the differential expression of the CCL2/CCR2 axis in OSCC." (PMID 41445742, 2025). "ENSA K63 lactylation upregulates STAT3/CCL2 signaling in tumor cells." (PMID 39883522, 2025). "We have recently demonstrated that immunosuppressive, IL17-secreting γδ T cells recruited to the tumor microenvironment by a CCL2-dependent mechanism upon CDK4/6 inhibition can repolarize tumor-associated macrophages toward a CX3CR1+ phenotype associated with resistance to therapy." (PMID 40662849, 2025). "We hypothesized that the Toe-Macs in NSCLC are pathogenic, in part due to enhanced expression of the key tumor-promoting factors NLRP3, IL-1β, TGF-β1, CCL2, IL-6, and PD-L1 (encoded by CD274)." (PMID 40794443, 2025). "Serum CCL2 levels serve as a potential tumor biomarker and correlate with disease advancement." (PMID 41445742, 2025). "Investigations into how p38 may regulate the expansion and recruitment of TAMs and MDSCs showed that p38α controls the tumor cell expression of cytokines and chemokines (e.g., CCL2, CXCL1, IL6, GM-CSF, G-CSF)." (PMID 41282257, 2025). "Analogous immunopathological patterns have been documented in breast malignancies, wherein IL-17A orchestrates a pro-tumorigenic cytokine-chemokine cascade—including IL-6, TGF-β, IL-1 isoforms, IL-8, TNF ligands, CXCL1, and CCL2—to reinforce a tumour-supportive stromal niche." (PMID 40943351, 2025). "Additionally, endothelial secretion of CCL2 controls metastasis by promoting tumor cell extravasation." (PMID 40111902, 2025). "Additionally, CCL2 induces the upregulation of programmed death ligand 1 (PD-L1) and programmed death ligand 2 (PD-L2) in tumor cells and immune cells, and inhibit the activation of CD8+ T cells mediated by PD-1 antibodies." (PMID 41341593, 2025). "However, recent studies indicate that CCL2 can also facilitate anti- tumor responses by enhancing monocyte and neutrophil functions, suggesting a context-dependent role of CCL2." (PMID 41326332, 2025). "Notably, IRF8-transduced tumor cells significantly reduce CCL2 secretion, resulting in decreased recruitment of myeloid cells into tumors via the CCL2–CCR2 axis." (PMID 41368628, 2025).
tumor (continued). "Using a xenograft SCID mice model these authors also demonstrated that CCL-2/MCP-1 is responsible for the monocyte recruitment into the tumor whereas IL-13 polarize these cells into M2 subset characterized by high expression of arginase-1 and low expression of inducible nitric oxide synthase (iNOS)." (PMID 40868818, 2025). "By secreting CCL2, tumor cells induce immune cells into the TME." (PMID 41376630, 2025). "Importantly, both KCa3.1 activation and LRRC8A inhibition significantly attenuated high [K+]e-induced CCL2 upregulation, further supporting their regulatory roles under tumor-like ionic conditions." (PMID 40806751, 2025). "The N2 markers include CCL17, CCL2, Arg, CCL5, and vascular endothelial growth factor (VEGF).The role of transforming growth factor-β (TGF-β) signaling within the tumor microenvironment (TME) has been implicated in the promotion of a pro-tumorigenic neutrophil phenotype (N2)." (PMID 40160822, 2025). "However, the chemokine CCL2 secreted by CAFs recruits MDSCs to the tumor site in a CCR2-dependent manner to form a pre-metastatic niche, thereby promoting cancer metastasis." (PMID 40131539, 2025). "In contrast, Ccl2-expressing IMs promote tumor growth by recruiting pro-tumorigenic recMacs." (PMID 40630529, 2025). "In PCa, both epithelial and stromal cells within the TME can release monocyte chemotactic protein (MCP)-1/C-C motif ligand (CCL2) along with other soluble factors, such as TGFβ, which fosters pro-tumor M2-like state polarization and correlates with tumor M2-like expansion and metastasis." (PMID 40389981, 2025). "The chemokine CCL2 induces cytoskeletal alterations in endothelial cells and is essential for recruitment and migration of neutrophil granulocytes across the endothelial barrier in mouse tumor models." (PMID 40111902, 2025). "Inhibit the ccl2/nf- κ B pathway in vivo to curb tumor growth and inhibit GBM angiogenesis." (PMID 40672375, 2025). "To confirm the inhibition of tumor growth associated with decreased chemokine expression in Ccn1‐KO tumor, we focused on CXC chemokines, including CXCL1, CXCL3, and CXCL5, which bind to CXCR2, as well as CCL2 and CCL7, which bind to CCR2." (PMID 40287974, 2025). "In addition to NF-κB, CCL2 expression is enhanced through activating mTOR, a downstream effector of the PI3K/AKT signaling pathway, which promotes tumor-associated macrophage (TAM) recruitment." (PMID 40940890, 2025). "Similarly, siRNA delivery using polyethylenimide-coated mesoporous silica nanoparticles effectively silenced TWIST1 and inhibited CCL2 expression, thereby inhibiting tumor growth in an in vivo model." (PMID 41341593, 2025). "Tumor-associated macrophages (TAMs) derived from blood monocytes, myeloid-derived suppressor cells, and tissue resident macrophages are induced and differentiated in tumor tissues by cytokines such as C-C motif chemokine ligand 2 (CCL2), CCL5, and colony-stimulating factor 1 (CSF-1)." (PMID 41002446, 2025). "Mechanistically, tumor-derived exosomes may carry chemokines (i.e., CCL2) that, by interacting with cognate receptors (i.e., CCR2), promote the uptake of exosomes by myeloid cells at metastatic sites." (PMID 41282257, 2025). "Given that MMP1 and S100A2 have been identified as important factors in the onset and development of PDAC, further research should investigate the role of MMP1/S100A2 in fostering a tumor-supportive microenvironment, particularly concerning CCL2+ macrophages and OMD+ fibroblasts." (PMID 40092486, 2025). "The CCL2-induced recruitment of macrophages to the tumor microenvironment reduces the efficacy of PD-L1/PD-1 inhibitors by delaying T-cell infiltration into the tumor." (PMID 41463161, 2025). "A key function of CCL2 is its ability to elicit an invasive phenotype in cancer cells and recruit monocytes to the tumor site, thereby implying that overexpression of CCL2 may have therapeutic implications in gynecological malignancies." (PMID 40636107, 2025).
tumor (continued). "Furthermore, CCL2 derived from tumor cells can activate the CCR2 receptor on vascular endothelial cells, inducing the JAK2/STAT5 and p38MAPK signaling pathways." (PMID 41341593, 2025). "In the TME, CCL2 secreted by cancer cells and stromal cells can activate downstream pathways, up-regulate the expression of anti-apoptotic proteins and cell cycle regulatory proteins to promote the survival and anti-apoptotic ability of tumor cells." (PMID 41341593, 2025). "Taken together, the increased expression of endothelial Ccl2, Ccl3, and Ccl4 is necessary for leukocyte transmigration into the lung tissue in the context of virus- or bacteria-induced inflammation, autoinflammation, and tumor-promoting metastasis." (PMID 40111902, 2025). "Tumor-associated macrophages (TAMs), in particular, become pro-angiogenic, producing vascular-modulating enzymes like MMP9 and growth factors such as VEGF, CCL2, and CXCL8." (PMID 40647432, 2025). "Intermittent hypoxia activates the NF-κB/HIF-1α pathway, increasing pro-inflammatory mediators like COX-2, CCL2, CXCL1, PGE2, and CSF1, these mediators recruit monocytes and neutrophils to the tumor microenvironment (TME), differentiating into TAMs and Tumor-Associated Neutrophils (TAN)." (PMID 41357522, 2025). "Mechanistically, researchers have demonstrated that TAMs activate the AKT signaling pathway in tumor cells by secreting chemokine ligand 2 (CCL2), which promotes the expression and nuclear localization of β-catenin and thus promotes EMT and CSC properties of TNBC tumor cells." (PMID 39889181, 2025). "The tumor cells in turn upregulated Ccl2 expression to reinforce monocyte recruitment." (PMID 40595293, 2025). "The downregulation of CCR2 in CD8+CD57+ T cells may affect their migration to TME enriched with chemokines (such as CCL2), thus weakening the local anti-tumor response." (PMID 41194936, 2025). "Other studies suggest that CCL2 is a potent pro-inflammatory chemokine that acts as a chemoattractant for myeloid cells and has been extensively studied as a predictor and potential driver of tumor cell growth and metastasis." (PMID 39940903, 2025). "Similarly, the activation of the TLR7/CCL2 axis in MCs recruits tumor-killing plasmacytoid dendritic cells." (PMID 41465542, 2025). "Furthermore, IL-1β and CCL2 mutually enhance each other’s production, forming a feedback loop that amplifies macrophage infiltration into tumor tissues." (PMID 41341593, 2025). "Consistently, lacidipine treatment or co‐administration with DOX/cisplatin significantly increased the mRNA expression of CCL5, CD274, CXCL10, and CXCL11 and decreased CCL2 mRNA levels in tumor tissues, thereby promoting immune cell infiltration and converting the “cold” into a “hot” tumor." (PMID 39585774, 2025). "Moreover, it was demonstrated that duplex miR-126/miR-126* suppresses the recruitment of inflammatory monocytes in an SDF-1α-dependent manner by inhibiting the expression of CCL2 in the tumor stroma." (PMID 40427136, 2025). "CCL2 attracts Tregs to the tumor microenvironment, where they exert immunosuppressive effects." (PMID 41463246, 2025). "Additionally, ETV4 regulates the expression of cytokines and cytokine receptors such as CCL2 and CXCR4, promoting tumor-associated macrophages (TAMs) and MDSCs recruitment and fostering an immunosuppressive microenvironment." (PMID 41502516, 2025). "In addition, the uptake of tumor microparticles by macrophages leads to the enhanced secretion of CCL2 to recruit further monocytes that predominantly differentiate into pro-tumor macrophages." (PMID 41440002, 2025). "Notably, Ccl2, known for its high expression within the tumor microenvironment and its pivotal role in recruiting TAMs, which generally resemble M2-like macrophages, was significantly upregulated in both the MFP and gWAT." (PMID 40526430, 2025). "RK3 downregulates PPARG expression in tumor cells, leading to a reduction in CCL2 secretion." (PMID 40867316, 2025).
tumor (continued). "Thus, the resulting CCL2 gradient activates CCR2-dependent signaling cascades that collectively foster a tumor-permissive niche." (PMID 41276817, 2025). "Beyond acute nucleic acid sensing, PARPi can induce treatment-related cellular senescence in tumor and stromal compartments, generating a senescence-associated secretory phenotype (SASP) enriched in IL6, IL8 or CXCL8, CCL2, GM-CSF, and members of the TGF beta family." (PMID 41488638, 2025). "Therefore, understanding the production mechanism and downstream effects of CCL2 in TME is not only the key to reveal the logic of tumor progression, but also provides a theoretical fulcrum for the development of CCL2 therapeutic strategies." (PMID 41341593, 2025). "CCL2 counteracted the anti-tumor immune response by recruiting immunosuppressive cells, such as regulatory T-cells and myeloid-derived suppressor cells, to the tumor site." (PMID 40535567, 2025). "Interestingly, we also observed reduced migration of Ccr2-/- monocytes towards tumor cell-derived supernatant from Ccl2KD cells, indicating an additional Ccl2-dependent mechanism." (PMID 39566333, 2025). "Specifically, the detection of the species Fusobacterium nucleatum, a constituent of this phylum, has been linked to increased expression of pro-inflammatory chemokines such as CXCL1, CXCL2, and CCL2, alongside enhanced angiogenesis and tumour gene expression alterations." (PMID 41516317, 2025). "Furthermore, CCL2 drives tumor invasion and distant metastasis by inducing angiogenesis, enhancing matrix metalloproteinase activity, and promoting premetastatic niche formation." (PMID 41341593, 2025). "A study revealed a correlation between elevated NLR and elevated CCL2 expression in tumor tissues." (PMID 40160822, 2025). "Moreover, the secreted levels of G-CSF and Ccl2 were notably reduced, but GM-CSF levels were significantly elevated in in CM from Ulk1 KO cells, indicating that Ulk1 determines to regulate tumor-intrinsic G-CSF, Ccl2 and GM-CSF secretion oppositely." (PMID 41408407, 2025). "At the same time, the reduction of the Msln+ tumor cluster 0 and the increased expression level of Ccl2+ in fibroblasts of the CAR-T-treated tumors could indicate a CAR-T specific response." (PMID 40568084, 2025). "In addition to IP-10, we also examined the effects of propolis and quercetin on another chemokine, MCP-1 (CCL2), which is involved in macrophage recruitment and the initiation of inflammation—processes that play a key role in the tumour microenvironment." (PMID 40733274, 2025). "The aim is to provide a theoretical basis for precise anti-tumor strategies targeting CCL2." (PMID 41341593, 2025). "Spatial transcriptomics showed that Ccl2 expression was concentrated within tumor regions." (PMID 40630529, 2025). "Also, Chemokine (C-C motif) ligand 2 (CCL2)-CCR2 axis is important in involving immune cells in tumor progression." (PMID 40472038, 2025). "In addition, this study determined that PD-L1 and chemokine ligand 2 (CCL2) were simultaneously increased in the tumor microenvironment." (PMID 41008336, 2025). "In addition, the TAM-secreted IL-6 stimulated the JAK2-STAT3 pathway in tumor cells and then upregulated the expression of CCL2 and EIF4A3." (PMID 40443670, 2025). "Moreover, TLR9-mediated tumor progression involves the implication of various chemokines, particularly CCL2 and CCL5, along with matrix metalloproteinases (MMP), such as MMP-2 and MMP-9." (PMID 41157253, 2025). "In addition, they stimulate cytokine release from leukocytes, endothelial cells, and tumor cells, increasing local levels of IL-8, CXCL12, and CCL2, which support tumor cell proliferation and angiogenesis." (PMID 40723273, 2025). "In TME, as a source of immunosuppressive cytokines and pro-tumor growth factors, tumor-associated macrophages (TAMs) are infiltrated and activated to express CSF1 and chemokine (C-C motif) ligand 2 (CCL2), thereby promoting tumor cell infiltration and metastasis." (PMID 40191727, 2025).